GHR (growth hormone receptor)
Diseases named in the same sentence as GHR in open-access papers (continued):
Sharing a sentence is not in itself a finding about the gene and the disease.
endometrial cancer (2 papers, 2021 to 2023). Primary or metastatic malignant neoplasm involving the endometrium (mucous membrane that lines the endometrial cavity). "Here we investigated the functional implications of nuclear translocation of the GHR in the human endometrial cancer cell-line, RL95-2, and human mammary epithelial cell-line, MCF-10A." (PMID 37043098, 2023). "To investigate the effects of nuclear translocation of the GHR, we first tested whether GHR nuclear translocation is observed in the endometrial cancer cell-line, RL95-2, and the mammary epithelial cell-line, MCF-10A." (PMID 37043098, 2023). "In endometrial cancer, autocrine hGH enhances the oncogenic characteristics in vitro and promotes the growth of RL95-2 tumors when GHR is overexpressed in vivo." (PMID 34178997, 2021).
gastric adenocarcinoma (2 papers, 2012 to 2022). "The more intense the expression of GHR in primary gastric adenocarcinoma was, the higher the PI and the lower the AI were found." (PMID 23554765, 2012). "Immunohistochemical analyses revealed that GHR was expressed in human primary gastric adenocarcinoma (36/48, 75.0%) and appeared to be upregulated, compared to the normal mucosa (28/48, 58.3%, P < 0.001)." (PMID 23554765, 2012). "The more intensely GHR was expressed in primary gastric adenocarcinoma, the higher the PI and the lower the AI was found." (PMID 23554765, 2012). "The aim of this study was to determine the expression of growth hormone receptor (GHR) in patients with primary gastric adenocarcinoma." (PMID 23554765, 2012). "Our results indicate that the frequency of GHR was significantly higher in primary gastric adenocarcinoma than that in normal gastric mucosa." (PMID 23554765, 2012). "The PI was 6.17%±1.85%, 10.50%±1.05%, 13.36%±2.41%, and 20.50%±4.08% in four groups of primary gastric adenocarcinoma graded 0, 1, 2, and 3 in GHR expression, respectively." (PMID 23554765, 2012).
glomerulosclerosis (2 papers, 2019 to 2023). A hardening of the kidney glomerulus caused by scarring of the blood vessels. "In addition, an animal test has shown that mice overexpressing GH develop glomerular hypertrophy, Albuminuria and glomerulosclerosis, while termination of GHR signaling could control GH expression." (PMID 37404805, 2023).
hepatic (2 papers, 2020 to 2026). "Interleukin 1 Beta (IL1B) was up-regulated along with GHR, and there is evidence that pro-inflammatory cytokines such as IL-1β are involved in hepatic growth hormone resistance during inflammation." (PMID 32101552, 2020). "Moreover, CUMS significantly disturbed amino acid metabolism, particularly lowered the concentration of L-Aspartic Acid, reduced the expressions of GHR/IGF-1 pathway in the liver, induced liver inflammation." (PMID 42222280, 2026).
Lipedema (2 papers, 2022). Disorder of adipose tissue characterized by symmetric and bilateral enlargement of the lower extremities due to abnormal deposition of subcutaneous fat often in obese women. "Mutations of GHR have been linked to partial GH deficiency and short stature, which have been confirmed in a single familial case of lipedema." (PMID 36551837, 2022). "Therefore, it is plausible that truncating variants, like the one identified by us, c.293G>A; p.Trp98* (rs1237134960) in GHR might be associated with lipedema." (PMID 35207755, 2022). "GHR antagonism or lack of GH function causes, in mice, an increase in subcutaneous adipose tissue similar to lipedema in humans." (PMID 35207755, 2022). "Another group sought to investigate the relationship between the common adipokines of adiponectin (ADIPOQ), ghrelin (GHR), resistin (RETN), and visfatin (VISF), as measured by ELISA and SAT thickness (evaluated by ultrasound) in lipedema patients." (PMID 36551837, 2022).
malignant metastatic melanoma (2 papers, 2017 to 2019). "Our study reaffirms and provides an explanation to the coexpression of GHR, MITF, and PGC1A in primary and metastatic melanoma patients." (PMID 31547367, 2019). "Previous reports have also found GHR and MITF as two of the top-20 upregulated genes in the PGC1A-high cohort of GSE7553 dataset of primary and metastatic melanoma patient gene expression." (PMID 31547367, 2019).
malocclusion (2 papers, 2024 to 2025). "The association between GHR polymorphisms and malocclusion phenotype was examined using the chi-square statistical method." (PMID 40311632, 2025). "This systematic review aims to determine the role of the growth hormone receptor (GHR) gene in skeletal malocclusion and its significant influence on the growth of the maxilla and the mandible in both sagittal and vertical dimensions." (PMID 38449954, 2024). "Specifically, GHR polymorphisms such as i526L (plate number 2, document number 2), along with other documented variations (document numbers 1 and 3), have been associated with class III skeletal malocclusion characterized by significant ramus elongation and corpus mandibula extension." (PMID 40311632, 2025).
meningioma (2 papers, 2021 to 2024). A generally slow growing tumor attached to the dura mater. "A small number of GHR antagonists have been used in an oncology settings in preclinical studies and the growth-inhibiting effects have been reported in colon, breast, and meningioma tumor xenografts, which suggested that GHR antagonism as a monotherapy is efficient in some tumor types." (PMID 34178997, 2021).
non-alcoholic fatty liver disease (2 papers, 2020 to 2025). "First, GHR has been demonstrated to be positively correlated with the onset of nonalcoholic fatty liver disease." (PMID 39950129, 2025). "For instance, a cross-sectional study with over 30,000 members revealed a positive correlation between GHR and the onset of nonalcoholic fatty liver disease." (PMID 39950129, 2025).
pituitary tumor (2 papers, 2011 to 2021). A benign or malignant neoplasm affecting the pituitary gland. "Nevertheless, our correlation analyses of natriuretic peptide gene expression in feline pituitary tumour samples reveal relationships between the different peptides and their receptors, as well as genes encoding physiological regulators of somatotrope function (D2R, SSTR5, and GHR)." (PMID 33499110, 2021). "NPPC expression was negatively correlated with pituitary tumour volume and SSTR5 expression, but positively correlated with D2R and GHR expression." (PMID 33499110, 2021).
Turner syndrome (2 papers, 2022). Turner syndrome is a chromosomal disorder associated with the complete or partial absence of an X chromosome. "A previous study conducted in 48 Turner syndrome girls showed that, compared with GHR fl/fl and fl/d3 genotype, GHR d3 allele homozygote was associated with a unique GH responsiveness and had a lower body mass index (BMI) level." (PMID 35402349, 2022). "The haplotypes of the GHR polymorphism were as follows: in GHD wt-wt (60%), wt-del3 (40%) and del3-del3 (0%), in SGA short stature wt-wt (44.5%), wt-del3 (44.5%) and del3-del3 (11%), in Turner syndrome wt-wt (38%), wt-del3 (56%) and del3-del3 (6%)." (PMID 35769084, 2022).
acute coronary syndrome (1 paper, 2025). Signs and symptoms related to acute ischemia of the myocardium secondary to coronary artery disease. "Another study explored the connection between acute coronary syndrome and GHR and discovered a high correlation between the two." (PMID 39950129, 2025).
Adamantinomatous Craniopharyngioma (1 paper, 2021). A craniopharyngioma consisting of broad strands, cords and bridges of a multistratified squamous epithelium with peripheral palisading of nuclei. "A recent case report showed that GHR was very lowly expressed in patients with adamantinomatous craniopharyngioma and deficiency in growth hormone led to the development of recurrence at 18 months after surgery." (PMID 34550275, 2021).
adenoma (1 paper, 2021). A neoplasm arising from the epithelium. "In addition, we cannot discard a direct action of GH, due to its essential role in triglyceride export from the liver; indeed, hepatic GHR deletion has been recently shown to lead to liver steatosis and adenoma formation." (PMID 33800837, 2021).
alopecia (1 paper, 2021). Hair loss usually from the scalp. "Absent GHR stimulation, and thus severely decreased IGF-1 levels, is associated with alopecia, telogen effluvium, frontal hairline recession, as well as severe HF structural changes like pili torti et canaliculi and trichorrhexis nodosa." (PMID 34948002, 2021).
bacterial sepsis (1 paper, 2024). "Our results establish a novel cytokine-independent mechanism for a decrease in GHR expression in bacterial sepsis." (PMID 39149693, 2024).
bladder tumors (1 paper, 2025). "While GHR levels may be lower in bladder tumors relative to normal tissue, higher expression of GHR within a tumor is still correlated with worse patient outcomes." (PMID 40806252, 2025).
brain injury (1 paper, 2018). Acute and chronic (see also brain INJURIES, CHRONIC) injuries to the brain, including the cerebral hemispheres, CEREBELLUM, and brain STEM. "We did not analyze whether GHR expression was upregulated in the contralateral intact cortex, but it has been recently described that during recovery from brain injury, there is an upregulation of GHR that may play a role in neuronal arborization and glial proliferation in the injured cortex." (PMID 29755514, 2018).
brain tumour (1 paper, 2022). "Ultimately, efforts to develop new GHR inhibitors specifically adapted to brain tumour treatment will be necessary." (PMID 35808822, 2022).
colon adenocarcinoma (1 paper, 2017). "In addition, the levels of GHR, which is expressed in both colonic epithelial and stromal cells, was also found to be increased in epithelial colon adenocarcinoma cells as compared to normal colon tissue." (PMID 29262609, 2017).
dental caries (1 paper, 2024). The decay of a tooth, in which it becomes softened, discolored, and/or porous. "Forth, genetic confounding between short stature and dental caries may exist, considering that GHR and BMP2 are associated with enamel dysplasia in the permanent teeth." (PMID 38248567, 2024).
depression (1 paper, 2026). "We found association of the GHR gene (false discovery rate -FDR- = 0.03, z = 4.2) and Reactome "RUNX1-regulated transcription of genes involved in myeloid cell differentiation pathway" (FDR = 0.016, beta = 1.2) with depression in GS." (PMID 41856978, 2026).
ductal carcinoma in situ (1 paper, 2019). "The same GHR-positive subsets appeared on 90% of 175 samples of human ductal carcinoma in situ (DCIS) lesions which are precursors to invasive breast cancer." (PMID 32382711, 2019).
ductal carcinomas (1 paper, 2016). "The lowest GHR expression among the histological subtypes of malignant tumors in the fresh frozen samples was found in ductal carcinomas (p = 0.036)." (PMID 27649560, 2016). "In FFPE samples simple carcinomas (p = 0.044), solid carcinomas (p = 0.005), carcinoma and malignant myoepithelioma (p = 0.036) and ductal carcinomas (p = 0.043) exhibited significantly lower GHR gene expression compared to the group of lobular hyperplasia." (PMID 27649560, 2016).
emphysema (1 paper, 2020). "Growth hormone receptor, an important hub in the network associated with percent emphysema, plays a role in preventing muscle atrophy." (PMID 32218378, 2020). "Alternatively, the network associated with percent emphysema had features such as growth hormone receptor, adipokines, amino acids, and lipids, suggesting that growth and metabolism may play a more important role in the pathogenesis of COPD." (PMID 32218378, 2020). "Leptin and adiponectin, nodes in the percent emphysema network with strong edges connecting them to growth hormone receptor, are both proteins released from adipose tissue." (PMID 32218378, 2020). "The strongest edges in the network connected growth hormone receptor with the other hubs mentioned demonstrating that growth hormone receptor has multiple pairwise correlations to percent emphysema." (PMID 32218378, 2020).
endometrial adenocarcinoma (1 paper, 2023). "Several studies have demonstrated that in preadipocytes and endometrial adenocarcinoma cells, the GHR can activate JAK2 and then promote the MAPK pathway." (PMID 37386516, 2023).
gallstones (1 paper, 2025). Solid crystalline precipitates in the biliary tract, usually formed in the gallbladder, resulting in the condition of cholelithiasis. "Keeping GHR levels within a certain range is associated with a lower incidence of gallstones in the general population." (PMID 39950129, 2025). "Below this value, every 1-unit increase in GHR is associated with a 61% increase in gallstone prevalence, while above this threshold, the association becomes statistically insignificant (P > 0.05)." (PMID 39950129, 2025). "This study emphasizes that keeping GHR levels within a healthy range is associated with a lower incidence of gallstones in the general population, with a particular emphasis on keeping GHR levels below 4.28; gallbladder stones are much less likely when GHR levels are below the threshold." (PMID 39950129, 2025). "Furthermore, the cross-sectional nature of this study limits the ability to establish causal relationships between GHR levels and gallstone prevalence." (PMID 39950129, 2025). "Association between GHR and gallstones in logistic regression analysis." (PMID 39950129, 2025). "At present, there could be more than one mechanism involved in the poorly understood underlying mechanisms of this positive association between gallstone occurrence and GHR." (PMID 39950129, 2025). "The association between gallstones and GHR by selected subgroups." (PMID 39950129, 2025). "Maintaining GHR below this threshold could serve as a clinical marker for preventing gallstones in populations at risk of metabolic disorders." (PMID 39950129, 2025). "Additionally, misclassification due to inaccurate recall or reporting may dilute the observed association between GHR and gallstones." (PMID 39950129, 2025). "Several statistical methods, including analysis of threshold effects, smoothed curve fitting, multiple logistic regression modeling, and subgroup analysis, were utilized to investigate the connection between GHR and gallstones." (PMID 39950129, 2025). "The observed inflection point of GHR = 4.28 suggests a threshold beyond which the relationship between GHR and gallstone prevalence weakens." (PMID 39950129, 2025). "The inflection point of GHR = 4.28 represents a critical threshold where the effect of GHR on gallstone prevalence plateaus." (PMID 39950129, 2025). "Thus, using information from the NHANES database, the study explored the potential link between GHR and gallstones." (PMID 39950129, 2025). "Third, to ascertain whether the relationship between GHR and gallstone prevalence varied by demographic characteristics, subgroup analyses were conducted." (PMID 39950129, 2025).
glioblastoma (1 paper, 2022). The most malignant astrocytic tumor (WHO grade IV). "Importantly, the analysis of Ivy Glioblastoma Atlas project dataset showed that GHR mRNA expression was significantly enriched in the infiltrating tumour (IT) anatomical structure compared to the core of the tumour, termed here cellular tumour (CT)." (PMID 35808822, 2022).
glomerulonephritis (1 paper, 2015). A renal disorder characterized by damage in the glomeruli. "Histopathological analysis revealed that causes of death in MuGHRKO mice were essentially unchanged, with similar rates of cancer and glomerulonephritis compared to controls, potentially reflecting the lack of alteration in IGF-1 levels when the GHR gene is disrupted in muscle." (PMID 26233957, 2015).
hair disorders (1 paper, 2021). "Further investigation of how GH and GHR stimulation affect hair follicle biology can guide feasible treatment options for different hair disorders." (PMID 34948002, 2021).
Hirsutism (1 paper, 2021). Abnormally increased hair growth referring to a male pattern of body hair (androgenic hair). "Excess GH levels, and therefore excess GHR stimulation and excess IGF-1 levels are associated with hypertrichosis and hirsutism." (PMID 34948002, 2021).
hypogonadism (1 paper, 2023). A disorder characterized by decreased function of the gonads. "This could represent one of the mechanisms by which IGF1R or GHR defects are associated with delayed puberty or hypogonadism." (PMID 37685880, 2023).
intrauterine growth restriction (1 paper, 2022). "Mutations in the GHR gene were found to cause a body height below −2 SD, from the mean for sex and age, whereas the mutations in the IGF1R gene were associated with low body height and intrauterine growth restriction (IUGR), and with being born SGA." (PMID 35627241, 2022).
Jarcho-Levin syndrome (1 paper, 2020). "However, our experts marked them as “Unrelated” due to the fact that these 2 conditions were grouped together in the past (both were previously referred to as Jarcho-Levin syndrome); they are considered as distinct conditions now, according to references from GHR (Genetic Home Reference)." (PMID 33006565, 2020).
joint disease (1 paper, 2024). "In this study, we are the first to report that GHR deficiency during adulthood (iGHR-/-) reduced trabecular thickness in the femoral epiphysis, a factor that no doubt impacts subchondral bone strength, the local loading environment, and ultimately, the progression joint disease." (PMID 38831184, 2024).
Lipid Metabolism Disorder (1 paper, 2020). "It is worth noting that mutation or abnormal expression of GHR often results in lipid metabolism disorder." (PMID 33519913, 2020).
liver failure (1 paper, 2019). A liver disease characterized by the liver losing or has lost all of its function. "These cytokines and liver failure cause inhibition of the expression and signaling of GHR in liver, which leads to reduced production of IGF-1 in liver and decreased IGF-1 levels in blood." (PMID 31791247, 2019).
lymphatic disorders (1 paper, 2026). "Future research will be necessary to determine the role of GHR antagonism in specific chronic inflammatory conditions and primary lymphatic disorders." (PMID 41549747, 2026).
microcephaly (1 paper, 2021). A congenital or acquired developmental disorder in which the circumference of the head is smaller than normal for the person's age and sex. "In current study, the upregulation of GHR suggests that the alteration of this gene by ZIKV may lead to neurological impairments causing reported diseases, which further indicate that MBP and GHR are directly involved in the brain development and microcephaly." (PMID 33891593, 2021).
muscle atrophy (1 paper, 2006). The loss of muscle tissue due to inactivity or disease. "This change in GHR expression is consistent with previous reports of decreased GHR mRNA in a compensatory overload model, and fiber-type specific increased GHR mRNA in a hindlimb suspension model of muscle atrophy." (PMID 17181869, 2006).
osteofibrous dysplasia (1 paper, 2020). A benign, usually self-limited fibro-osseous lesion of the bone that affects infants and children. "Here, we report that growth hormone receptor (GHR) is overexpressed in OS samples compared with osteofibrous dysplasia." (PMID 31725956, 2020). "Herein, we speculate that GHR may be the biomarker of patients with OS with osteofibrous dysplasia and provide a promising avenue for prognostic and therapeutic strategies to improve patient outcomes." (PMID 31725956, 2020). "Our data suggest that GHR promoted migration via the EMT‐dependent pathway; meanwhile, the involvement of GHR in cell migration may lead to osteofibrous dysplasia." (PMID 31725956, 2020).
polycystic kidney disease (1 paper, 2013). A usually autosomal dominant and less frequently autosomal recessive genetic disorder characterized by the presence of numerous cysts in the kidneys leading to end-stage renal failure. "SMN, GHR and PKHD1 gene deletions respectively associated to spinal muscular atrophy, responsiveness to growth hormone and polycystic kidney disease were also detected using GStream." (PMID 23844243, 2013).